KRT19P3 (keratin 19 pseudogene 3)
Gene: Processed pseudogene on chromosome 4 (109,879,070 to 109,879,897, reverse strand). Ensembl gene ENSG00000249681.
Diseases named in the same sentence as KRT19P3 in open-access papers:
KRT19P3 is named in the same sentence as 7 diseases in open-access papers, as found by Europe PMC text mining. Sharing a sentence is not in itself a finding about the gene and the disease. The quoted sentences say what the papers report.
gastric cancer (5 papers, 2020 to 2024). A primary or metastatic malignant neoplasm involving the stomach. "Regarding the KRT19P3 played an important part in gastric cancer cell migration and invasion capability, we investigated the role of KRT19P3 on BC cells." (PMID 35059320, 2021). "KRT19P3-mediated enhancement of COPS7A protein stability accounted for its roles in suppressing gastric cancer." (PMID 32185172, 2020). "LncRNA KRT19P3 has been reported to inhibit the progression of gastric cancer." (PMID 35059320, 2021). "Zheng and colleagues also found that KRT19P3 suppressed gastric tumor growth and metastasis through a COPS7A-regulated NF-κB pathway, suggesting that COPS7A acts as a suppressor of gastric cancer." (PMID 38466642, 2024). "KRT19P3/COPS7A dysregulates the NF-κB signaling pathway through the inhibition of IkBa ubiquitination and thus promotes metastasis in gastric cancer." (PMID 33050646, 2020). "In gastric cancer, as in the previous CYTOR, lncRNA KRT19P3 has also been reported to be related to NF-κB signaling." (PMID 33050646, 2020). "KRT19P3 was less expressed in gastric cancer tissues compared to normal gastric tissues." (PMID 35059320, 2021).
bladder cancer (2 papers, 2014 to 2021). "It was confirmed that KRT19P3 was highly expressed in bladder cancer tissues compared to normal bladder tissues." (PMID 35059320, 2021). "For further validation of microarray results, qPCR was performed to evaluate the expression patterns of TNXA, CTA-134P22.2, CTC-276P9.1 and KRT19P3 in a total of 51 patients with bladder cancer." (PMID 24944692, 2014). "Data analysis showed that KRT19P3 was upregulated and TNXA, CTA-134P22.2 and CTC-276P9.1 were downregulated in bladder cancer samples compared with matched normal tissues." (PMID 24944692, 2014).
breast carcinoma (1 paper, 2021). "Subsequently, we confirmed the differential expression of KRT19P3 in breast cancer tissues and para cancer tissues by clinical samples." (PMID 35059320, 2021).
tumor (3 papers, 2021). "The RT-qPCR result showed that the median expression of KRT19P3 was 0.0063 in BC tissues and 0.0550 in non-tumor tissues." (PMID 35059320, 2021). "Increased expression of KRT19P3 markedly inhibited the proliferation, migration, and invasion rate of BC cells in vitro and tumor growth of BC in vivo." (PMID 35059320, 2021). "KRT19P3 was 8.7302-fold higher in para cancer tissues than in tumor tissues." (PMID 35059320, 2021). "Vitro experiments showed that KRT19P3 functions as a tumor suppressor gene." (PMID 35059320, 2021). "AUC was 0.9296, indicating that KRT19P3 could better differentiate BC tissues from non-tumor tissues." (PMID 35059320, 2021). "The expression of KRT19P3 was higher in non-tumor tissues than in BC tissues." (PMID 35059320, 2021).
cancer (1 paper, 2021). A tumor composed of atypical neoplastic, often pleomorphic cells that invade other tissues. "The ROC curve was drawn according to the expression of KRT19P3 in BC and para cancer tissues and the AUC under the curves was calculated." (PMID 35059320, 2021). "In the present study, we first discovered that KRT19P3 was downregulated in BC tissues compared with para cancer tissue." (PMID 35059320, 2021). "The expression of KRT19P3 in BC tissues and para cancer tissues was plotted by the ROC curve." (PMID 35059320, 2021). "Then we showed that KRT19P3 could be used as a marker to differentiate BC from para cancer tissue." (PMID 35059320, 2021).
KRT19P3 also shares sentences with these, for which no sentence is quoted: gastric tumor (1 paper); lymph node metastasis (1).